PIGG (phosphatidylinositol glycan anchor biosynthesis class G (EMM blood group))
Description:
Catalytic subunit of the ethanolamine phosphate transferase 2 complex that transfers an ethanolamine phosphate (EtNP) from a phosphatidylethanolamine (PE) to the 6-OH position of the second alpha-1,6-linked mannose of a 2-acyl-6-[6-phosphoethanolamine-alpha-D-mannosyl-(1->2)-alpha-D-mannosyl-(1->6)-2-phosphoethanolamine-alpha-D-mannosyl-(1->4)-alpha-D-glucosaminyl]-1-(1-radyl,2-acyl-sn-glycero-3-phospho)-1D-myo-inositol (also termed H7) intermediate to generate a 2-acyl-6-[6-phosphoethanolamine-alpha-D-mannosyl-(1->2)-6-phosphoethanolamine-alpha-D-mannosyl-(1->6)-2-phosphoethanolamine-alpha-D-mannosyl-(1->4)-alpha-D-glucosaminyl]-1-(1-radyl,2-acyl-sn-glycero-3-phospho)-1D-myo-inositol (also termed H8) and participates in the eleventh step of the glycosylphosphatidylinositol-anchor biosynthesis.
Synonyms: GPI7; FLJ20265; LAS21; EMM; MRT53; NEDHSCA; PRO4405; RLGS1930
Tractability: Antibody: UniProt predicts a signal peptide or a membrane-spanning region. PROTAC: ubiquitination databases record sites on it; its protein half-life has been measured.
Gene: Protein-coding gene on chromosome 4 (499,210 to 540,200, forward strand). Ensembl gene ENSG00000174227.
Subcellular location: Endoplasmic reticulum membrane
Pathways (Reactome):
Metabolism of proteins: Synthesis of glycosylphosphatidylinositol (GPI)
Gene Ontology:
Molecular function: mannose-ethanolamine phosphotransferase activity; protein binding; transferase activity; phosphotransferase activity, for other substituted phosphate groups
Biological process: GPI anchor biosynthetic process
Cellular component: endoplasmic reticulum; endoplasmic reticulum membrane; membrane
Genetic constraint (gnomAD): Loss-of-function variants: 63 observed, 69.99 expected, observed/expected ratio (o/e) 0.9, 90% interval 0.73 to 1.11. The upper end of that interval is the gene's LOEUF score, 1.11, which puts it in group 4 of 6, group 1 being the genes least tolerant of losing a copy. Missense variants: 1,147 observed, 1,151.2 expected, observed/expected ratio (o/e) 1, 90% interval 0.95 to 1.05. Synonymous variants: 491 observed, 492.33 expected, observed/expected ratio (o/e) 1, 90% interval 0.93 to 1.08.
Homologues: Orthologues: macaque PIGG (93% identical), chimpanzee PIGG (91% identical), dog PIGG (84% identical), rat Pigg (81% identical), mouse Pigg (80% identical), guinea pig PIGG (78% identical), rabbit PIGG (72% identical), tropical clawed frog pigg (63% identical), zebrafish pigg (61% identical), pig PIGG (58% identical), Drosophila melanogaster PIG-G (27% identical), Caenorhabditis elegans pigg-1 (23% identical).
Diseases named in the same sentence as PIGG in open-access papers:
PIGG is named in the same sentence as 21 diseases in open-access papers, as found by Europe PMC text mining. Sharing a sentence is not in itself a finding about the gene and the disease. The quoted sentences say what the papers report.
autoimmune hepatitis (4 papers, 2023 to 2025). Hepatitis caused by autoantibodies. "We and others have shown that pIgG can be associated with false positive results even in commercially available autoantibody ELISAs for autoimmune liver diseases." (PMID 37809342, 2023). "This study evaluated the agreement between three commercial ELISAs and the reference techniques and the impact of polyreactive immunoglobulin G (pIgG), a recently described phenomenon in autoimmune hepatitis, on commercial ELISAs." (PMID 37340049, 2023).
Intellectual disability (2 papers, 2021). "PIGG loss of function mutations have only recently been reported to be responsible for neurologic phenotypes including seizures, developmental delay, intellectual disability, and hypotonia; this is an active area of investigation." (PMID 34535746, 2021).
liver disease (2 papers, 2024 to 2025). "As IgG from children with untreated AIH exhibited similar polyreactivity as published in adults, we continued the evaluation of pIgG in a multi-center cohort of children with AIH, non-AIH liver disease (non-AIH LD) and HC." (PMID 38976227, 2024).
autosomal recessive intellectual developmental disorder-53 (1 paper, 2022). "Biallelic pathogenic variants in the PIGG gene have been reported in patients with autosomal recessive intellectual developmental disorder-53." (PMID 35440058, 2022).
Hepatitis (1 paper, 2023). Inflammation of the liver. "Nonetheless, patients with hepatitis after mRNA-1273 (n = 12) had more severe histological injury (Ishak necroinflammation grade 11 vs. 9, p = 0.001), higher SMA titers (≥1:160 in 8/8 vs. in 2/8, p = 0.007) and higher pIgG concentrations (median 1.6 vs. 0.9, p = 0.012) than after BNT162b2 (n = 30)." (PMID 36440259, 2023).
cancer (2 papers, 2018 to 2021). A tumor composed of atypical neoplastic, often pleomorphic cells that invade other tissues. "There are no data in cancer studies concerning SLC8B1 (encoding NCLX protein) and PIGG." (PMID 29386520, 2018).
PIGG also shares sentences with these, for which no sentence is quoted: candidiasis (2 papers); genetic diseases (2); infection (2); autism (1); Autoimmunity (1); breast carcinoma (1); Candida infection (1); developmental delay (1); epilepsy (1); fungal infections (1); hepatopathies (1); infectious disease (1); metabolic disorder (1); neurological disorders (1); Stroke (1).